TSPAN33 (tetraspanin 33)
Description:
Part of TspanC8 subgroup, composed of 6 members that interact with the transmembrane metalloprotease ADAM10. This interaction is required for ADAM10 exit from the endoplasmic reticulum and for enzymatic maturation and trafficking to the cell surface as well as substrate specificity. Different TspanC8/ADAM10 complexes have distinct substrates. Plays an important role in normal erythropoiesis (By similarity). It has a role in the differentiation of erythroid progenitors (By similarity). Negatively regulates ligand-induced Notch activity probably by regulating ADAM10 activity. Mediates docking of ADAM10 to zonula adherens by interacting with ADAM10 and, in a PDZD11-dependent manner, with the zonula adherens protein PLEKHA7.
Synonyms: Tspan-33; PEN; MGC50844; Penumbra; PEN.
Tractability: Antibody: UniProt places it where antibodies can reach, with high confidence; its Gene Ontology location is reachable by antibodies, with high confidence; UniProt predicts a signal peptide or a membrane-spanning region.
Gene: Protein-coding gene on chromosome 7 (129,144,690 to 129,169,699, forward strand). Ensembl gene ENSG00000158457.
Subcellular location: Cell membrane; Cell junction, adherens junction; Cytoplasm
Subcellular location (Human Protein Atlas): Microtubules
Pathways (Reactome):
Metabolism of proteins: Amyloid fiber formation
Gene Ontology:
Molecular function: enzyme binding; protein binding
Biological process: pore complex assembly; protein localization to plasma membrane; protein maturation
Cellular component: cytoplasm; plasma membrane; pore complex; endoplasmic reticulum lumen; adherens junction; cell surface; membrane; tetraspanin-enriched microdomain
Genetic constraint (gnomAD): Loss-of-function variants: 22 observed, 35.31 expected, observed/expected ratio (o/e) 0.62, 90% interval 0.44 to 0.89. The upper end of that interval is the gene's LOEUF score, 0.89, which puts it in group 3 of 6, group 1 being the genes least tolerant of losing a copy. Missense variants: 245 observed, 322.79 expected, observed/expected ratio (o/e) 0.76, 90% interval 0.68 to 0.84. Synonymous variants: 106 observed, 121.06 expected, observed/expected ratio (o/e) 0.88, 90% interval 0.75 to 1.03.
Homologues: Orthologues: chimpanzee TSPAN33 (100% identical), macaque TSPAN33 (99% identical), rat Tspan33 (97% identical), mouse Tspan33 (97% identical), rabbit TSPAN33 (96% identical), dog TSPAN33 (96% identical), pig TSPAN33 (94% identical), guinea pig TSPAN33 (90% identical), tropical clawed frog tspan33 (83% identical), zebrafish tspan33a (72% identical). Paralogues in human: TSPAN17 (36% identical), TSPAN5 (35% identical), TSPAN14 (33% identical), TSPAN15 (29% identical), TSPAN4 (27% identical), TSPAN3 (25% identical), TSPAN11 (24% identical), CD63 (24% identical), TSPAN9 (24% identical), TSPAN10 (23% identical), TSPAN7 (23% identical), CD53 (23% identical), and 20 more.
Diseases named in the same sentence as TSPAN33 in open-access papers:
TSPAN33 is named in the same sentence as 19 diseases in open-access papers, as found by Europe PMC text mining. Sharing a sentence is not in itself a finding about the gene and the disease. The quoted sentences say what the papers report.
lymphoma (3 papers, 2024 to 2025). A malignant (clonal) proliferation of B- lymphocytes or T- lymphocytes which involves the lymph nodes, bone marrow and/or extranodal sites. "The expression of TSPAN33 is increased in some autoimmune diseases and lymphomas, and it also participates in the inflammatory process by regulating the expression of proinflammatory genes and the activation of different immune cells." (PMID 40305362, 2025). "Among the differentially expressed glycoproteins, tetraspanin-33 (TSPAN33) was identified as a candidate selectively upregulated on activated B cells and certain lymphoma cells, but with limited expression on naïve and memory B cell subsets." (PMID 41164194, 2025).
acute lymphoblastic leukemia (1 paper, 2016). Leukemia with an acute onset, characterized by the presence of lymphoblasts in the bone marrow and the peripheral blood. "Additionally, siRNA mediated knockdown of Tspan33 in HeLa cells reduced the γ-secretase dependent cleavage of a constitutively active, truncated form of Notch1 and that of T-cell acute lymphoblastic leukemia (T-ALL) Notch1 oncogenic mutants." (PMID 28066176, 2016).
Arterial thrombosis (1 paper, 2022). The formation of a blood clot inside an artery. "Theoretically, a therapeutic strategy designed to activate Tspan15/ADAM10 or Tspan33/ADAM10 may provide a novel treatment for arterial thrombosis, since irreversible shedding of GPVI would render platelets non-responsive to collagen." (PMID 35269584, 2022).
ischemic stroke (1 paper, 2022). A stroke disorder caused by obstruction of blood flow to the brain, due to thrombotic (local blood clot formation) or embolic (due to a blood clot or other material traveling from another site) event. "In conclusion, a major finding of this study is the identification of Tspan15/ADAM10 and Tspan33/ADAM10 as molecular scissors for GPVI, a clinically relevant antiplatelet target for myocardial infarction and ischemic stroke." (PMID 35269584, 2022).
scleroderma (1 paper, 2021). Scleroderma is a rare autoimmune connective tissue disorder characterized by abnormal hardening of the skin and, sometimes, other organs. "We note 38 of the genes found expressed in T cells TADs encompassing the scleroderma associated SNPs were also found to be differentially expressed in Dolcino’s study, including BSG, FCER2, GPA33, MAP2K7, SCAMP2, and TSPAN33." (PMID 33894768, 2021).
cardiovascular diseases (1 paper, 2025). "TSPAN33 participates in inflammatory reactions through immunoregulation and cell adhesion-related pathways, but its specific mechanism in cardiovascular diseases needs further study." (PMID 40305362, 2025). "However, there are no reports on the pathological role of TSPAN33 in cardiovascular diseases." (PMID 40305362, 2025).
colorectal (1 paper, 2020). "Additionally, the genes that were highly expressed in colorectal patients are TSPAN2, TSPAN5, TSPAN12, TSPAN28, TSPAN29, and TSPAN33." (PMID 32694936, 2020).
TSPAN33 also shares sentences with these, for which no sentence is quoted: autoimmune disease (2 papers); tumor (2); Alzheimer disease (1); breast carcinoma (1); cancer (1); childhood leukemia (1); colorectal cancer (1); coronary artery disease (1); glioblastoma multiforme (1); inflammatory bowel disease (1); myocardial infarction (1); non-small cell lung carcinoma (1).